IGF2 (insulin like growth factor 2)
Diseases named in the same sentence as IGF2 in open-access papers (continued):
Sharing a sentence is not in itself a finding about the gene and the disease.
Perlman syndrome (3 papers, 2018 to 2024). Perlman syndrome is characterized principally by polyhydramnios, neonatal macrosomia, bilateral renal tumors (hamartomas with or without nephroblastomatosis), hypertrophy of the islets of Langerhans and facial dysmorphism. "Interestingly, IGF2 overexpression has been observed in two rare conditions characterized by fetal overgrowth, namely Beckwith-Wiedemann and Perlman syndrome; however, its potential role in acro-gigantism still requires elucidation." (PMID 37891382, 2024). "Upregulation of IGF2 in nephron progenitor cells may lead to Perlman syndrome, a rare disease including serious kidney disease." (PMID 35596061, 2022). "In addition, upregulation of IGF2 has been proven to lead to Perlman syndrome, a disease related to kidney injury, in mouse nephron progenitor cells." (PMID 35596061, 2022).
psoriasis (3 papers, 2013 to 2023). An autoimmune condition characterized by red, well-delineated plaques with silvery scales that are usually on the extensor surfaces and scalp. "And the result displayed that three hub genes (GNAS, AUC = 0.709; IGF2, AUC = 0.644; and SNRPN, AUC = 0.926) had a credible diagnostic value for psoriasis." (PMID 37935955, 2023). "We first identified three hub genes, including SNRPN, IGF2, and GNAS, which could be potential therapeutic targets of psoriasis and T2D." (PMID 37935955, 2023).
psychosis (3 papers, 2019 to 2024). "Of particular interest will be studies examining whether hypomethylation at the IGF2 enhancer extends from a risk factor to a prognostic marker in peripheral tissues for the development of psychosis." (PMID 31053723, 2019). "Our data suggests that epigenetic activation of the enhancer at IGF2 may enhance dopamine synthesis associated with major psychosis." (PMID 31053723, 2019). "The hypomethylated IGF2 locus in major psychosis overlapped an enhancer in the adult frontal cortex (data from NIH Roadmap Epigenomics Project)." (PMID 31053723, 2019). "We observe prominent hypomethylation of an enhancer within the insulin-like growth factor 2 (IGF2) gene in major psychosis neurons." (PMID 31053723, 2019). "In another study, when neurons were extracted from the prefrontal cortex of schizophrenic and bipolar individuals (n = 55 cases and 27 controls), the hypomethylation of an enhancer in insulin-like growth factor 2 gene (IGF2) was observed to be present in the neurons of psychosis patients." (PMID 34299291, 2021). "The epigenetic regulatory connection between IGF2 and TH may also help explain the co-occurrence of neuronal structure and synaptic abnormalities with dopamine dysregulation in major psychosis patients." (PMID 31053723, 2019). "Notably, two of the top differentially methylated regions in major psychosis neurons were located at the 3′ end of the IGF2 gene (Šidák p < 10−3)." (PMID 31053723, 2019). "We propose that improper epigenetic control of an IGF2 enhancer may simultaneously contribute to dopamine-mediated psychotic symptoms and synaptic structural deficits in major psychosis." (PMID 31053723, 2019). "Here, the authors characterise the hypomethylation of an enhancer within the insulin-like growth factor 2 gene in neurons of patients with major psychosis and provide evidence that this enhancer targets the tyrosine hydroxylase gene, responsible for dopamine synthesis." (PMID 31053723, 2019). "Therefore, in neurons of major psychosis patients, epigenetic changes facilitating a recruitment of the enhancer at IGF2 for activation of TH, may, in tandem, impede IGF2 regulation." (PMID 31053723, 2019).
seminoma (3 papers, 2016 to 2024). A radiosensitive malignant germ cell tumor found in the testis (especially undescended), and extragonadal sites (anterior mediastinum and pineal gland). "Intriguingly, a heightened proportion of IGF2+ myofibroblasts was discernible in metastatic non-seminomas, corroborating their comparably undifferentiated phenotype." (PMID 39528470, 2024). "Second, hypomethylation of chromosome 11p15.5, which occurs in 38.5% of RSS cases and leads to hypomethylation of the IGF2/H19 imprinting control region (ICR), may be a risk factor for seminoma." (PMID 27034882, 2016). "In order to further elucidate the relationships among distinct cellular constituents within non-seminomas, we used gene signatures associated with MMP12+ macrophage, IGF2+ myofibroblast and B cell to score non-seminoma samples from TCGA TGCT dataset." (PMID 39528470, 2024). "Moreover, our findings confirmed a strong association between oligozoospermia and imprinting defects (herein, on H19/IGF2, MEG3/DLK1, and SNURF DMRs for oligozoospermic patients with or without seminoma)." (PMID 30340650, 2018).
Serous Ovarian Cancer (3 papers, 2013 to 2025). "An analysis of The Cancer Genome Atlas (TCGA) data in the serous ovarian cancer cohort showed that high IGF2 mRNA expression is significantly associated with shortened interval to disease progression and death, clinical indicators of drug resistance." (PMID 24932685, 2014).
thyroid tumor (3 papers, 1999 to 2022). A benign or malignant neoplasm affecting the thyroid gland. "In thyroid tumors, the high expression of IGF2BP3 sustains IGF2 levels and leads to an increased sensitivity to OSI-906." (PMID 29731738, 2018).
adrenal carcinoma (2 papers, 2012 to 2016). A carcinoma involving a adrenal gland. "Metformin interferes with the proliferative autocrine loop of IGF2/IGF-1R, which supports adrenal cancer growth." (PMID 27391065, 2016). "Altogether, these data strongly suggest that despite marked overexpression in adrenal carcinomas, Igf2 is unlikely to play a major role in either tumour initiation or progression in the adrenal cortex." (PMID 22952916, 2012). "In vitro studies on adrenal carcinoma cell lines with increased IGF2 expression showed that blocking IGF1R activity resulted in both decreased proliferation and induction of apoptosis, indicating that IGF2 was involved in the control of both processes." (PMID 22952916, 2012).
Adrenal insufficiency (2 papers, 2014 to 2020). Insufficient production of steroid hormones (primarily cortisol) by the adrenal glands. "Concurrent normal to high morning cortisol and normal response on cosyntropin stimulation can rule out adrenal insufficiency and suggest NICTH secondary to IGF-2." (PMID 24934576, 2014).
AIDS (2 papers, 2005 to 2015). A syndrome resulting from the acquired deficiency of cellular immunity caused by the human immunodeficiency virus (HIV). "The association of low plasma IGF1 (or IGF2) and high IGFBPs with HIV progression (AIDS, low CD4 T cell counts) have been well established." (PMID 25890304, 2015).
Ascites (2 papers, 2024 to 2025). Accumulation of fluid in the peritoneal cavity (between the layers of the peritoneum that lines the abdomen). "Consistent with our results, one of these other studies identified the association of high IGF2 above the median in serum and ascites to be associated with worse prognosis." (PMID 41007637, 2025). "Levels of IGF-1 and IGF-2 in serum and ascites were all associated with mortality in univariable analyses." (PMID 38396692, 2024). "To validate and quantify the observed differential IGF2 expression at the protein level, we compared IGF2 protein levels in the initial and recurrent ascites." (PMID 41007637, 2025). "The limitations of this study include the small number of ascites samples in the initial vs. recurrent comparison groups and the serum samples used to evaluate the prognostic significance of IGF2." (PMID 41007637, 2025). "IGF2 exhibited the highest level of differential expression with greater expression in the recurrent compared to initial ascites groups." (PMID 41007637, 2025).
asthenospermia (2 papers, 2022 to 2024). "In male gametes, data are scarce; however, DNA fragmentation and asthenospermia are associated with hypermethylation of the paternally imprinted gene, IGF-2." (PMID 39765848, 2024). "Compared to the methylations detected in the CpG sites of the IGF-2 in the normozoospermia group, four sites showed hypomethylation and two sites showed hypermethylation in the corresponding regions of the asthenospermia group." (PMID 36357889, 2022). "We assessed the DNA methylation patterns of the selected gene regions using the MethylTarget technique, and detected 323 CpG sites, of which only 6 (2 in IGF-2, 1 in KCNQ1, and 3 in MEST) were significantly different between the mild asthenospermia and normozoospermia groups." (PMID 36357889, 2022).
Autoimmunity (2 papers, 2021). The occurrence of an immune reaction against the organism's own cells or tissues. "In mice, the transplantation of an Aire-/- thymic stromal compartment induces organ-specific autoimmunity paralleled by the decrease in the intrathymic transcription of genes encoding neuroendocrine self-antigens (oxytocin, IGF2) and many TRAs." (PMID 33415360, 2021). "Similarly, autoimmunity caused by recognition of IGF2, a factor essential for foetal growth and development, has also not been reported whereas insulin serves as a primary autoantigen in the context of type 1 diabetes (T1D)." (PMID 33415360, 2021).
benign adrenal neoplasms (2 papers, 2016 to 2021). "Among markers that can distinguish ACC from benign adrenal neoplasms, insulin-like growth factor 2 (IGF-2) is the most frequently studied, with overexpression in up to 90% of ACC (see also sections ‘Methylome’, ‘Transcriptome’ and ‘DNA mutations’)." (PMID 34503194, 2021).
Cardiomyopathies (2 papers, 2021 to 2022). "In sum, H19/Igf2 LOI in mice results in transient neonatal cardiomegaly and then a progressive cardiomyopathy." (PMID 34402430, 2021).
Cerebral ischemia (2 papers, 2012 to 2024). Restriction of arterial blood supply to the brain associated with insufficient oxygenation to support the metabolic requirements of the tissue. "The differential expression of IGF-2, TIMP-2, VEGFA, and bFGF observed in our study highlights the complex nature of the biological response to cerebral ischemia and the potential influence of therapeutic interventions." (PMID 38178130, 2024).
cholesteatoma (2 papers, 2021 to 2023). A pathologic process characterized by the proliferation of keratinizing squamous epithelium resulting in the accumulation of keratin and cells in the middle ear and/or mastoid. "The expression of the growth factors KGF, EGF, EREG, IGF-2 and HGF was significantly higher in fibroblasts, particularly when derived from cholesteatoma." (PMID 33627146, 2021). "Despite this huge biological variance, a significantly higher expression in ME-CSCs and ME-CFs derived from cholesteatoma tissue could be observed for the growth factors KGF and IGF-2 (p ≤ 0.05, p ≤ 0.01 respectively)." (PMID 33627146, 2021). "Under standard culture conditions, we detected a tissue-independent higher expression of IL-1β and IL-8 in stem cells, an upregulation of KGF and IGF-2 in both cell types derived from cholesteatoma and higher expression of TLR4 in stem cells derived from cholesteatoma tissue." (PMID 33627146, 2021). "When comparing the cells derived from cholesteatoma tissue with the cells from auditory canal skin, we could observe a significant upregulation of the two growth factors KGF and IGF-2 and a similar trend for IL-1α and HGF." (PMID 33627146, 2021).
COVID-19 (2 papers, 2022 to 2025). A disease caused by infection with severe acute respiratory syndrome coronavirus 2. "Together, these results indicate reduced expression of IGFBP2 and its selective ligands IGF1 and IGF2 specifically in AEC2 cells from patients diagnosed with severe or moderate COVID-19." (PMID 40121473, 2025).
Down syndrome (2 papers, 2023). "A study analysing astrocyte protein secretion and gene expression in three mouse models of genetic neurodegenerative diseases (Rett, Fragile X and Down syndrome) showed that astrocytes secrete the IGF2 inhibitory protein IGFBP2, causing learning and memory failure." (PMID 37108327, 2023). "Another study also predicted that IGF2 was involved in genetic crosstalk between PD and Down Syndrome, indicating the importance of IGF2 in the pathogenesis of PD." (PMID 37051594, 2023).
embryonal carcinoma (2 papers, 2020 to 2021). A non-seminomatous malignant germ cell tumor characterized by the presence of large germ cells with abundant cytoplasm resembling epithelial cells, geographic necrosis, high mitotic activity, and pseudoglandular and pseudopapillary structures formation. "A previous study of an embryonal carcinoma cell line reported that IGF2 activates translation initiation." (PMID 33318299, 2020).
experimental autoimmune encephalomyelitis (2 papers, 2023 to 2026). An autoimmune demyelinating disease of the central nervous system that is produced experimentally in animals by the injection of homogenized brain or spinal cord in Freund's adjuvant. "When exposed to low concentrations of IGF-2, maturing macrophages are committed to oxidative phosphorylation (OXPHOS) and consequently increase the expression of PD-L1, which is required for the beneficial effect of IGF-2 on experimental autoimmune encephalomyelitis." (PMID 36973490, 2023).
fatty liver (2 papers, 2019 to 2021). "Even though insulin-like growth factor 2 (IGF2) has been reported to be overexpressed innonalcoholic fatty liver disease (NAFLD), its role in the progression of NAFLD and thepotential mechanism remain largely unclear." (PMID 33988719, 2021).
fragile X syndrome (2 papers, 2020 to 2021). A genetic syndrome caused by mutations in the FMR1 gene which is responsible for the expression of the fragile X mental retardation 1 protein. "Igf2 codes IGF2, which is one member of the insulin signaling pathway and its deficiency can lead to serious cognition dysfunction and it is involved in impaired cognition in Fragile X syndrome." (PMID 33040050, 2020).
head and neck cancer (2 papers, 2015 to 2021). A primary or metastatic malignant neoplasm affecting the head and neck. "Compared with HNSCC tissues (n=10) from head and neck cancer tissue array (US Biomax Inc., Rockville, MD), all six samples from cixutumumab-treated patients showed markedly increased numbers of macrophages, fibroblasts and VE cells along with IGF-2 expression." (PMID 26465273, 2015).
hyperlipidemia (2 papers, 2013 to 2021). "Importantly, A2M, APP, CLU, IGF2 and PLAU are not among the hyperlipidemia associated genes, they are retrieved only after obtaining the disease module with DIAMOND." (PMID 34824199, 2021).
hypothyroidism (2 papers, 2020 to 2025). Abnormally low levels of thyroid hormone. "Expression of the major IGF ligands, IGF1 and IGF2, was not altered by MMI‐induced hypothyroidism, but six out of seven of the assessed IGFBPs were temporally dysregulated in the hypothyroid fetal LVR, with two of the IGFBPs temporally dysregulated in the fetal KID." (PMID 40693299, 2025).
juvenile nasopharyngeal angiofibroma (2 papers, 2017 to 2018). "Furthermore, the IGF2/H19 imprinting changes were correlated with juvenile nasopharyngeal angiofibroma (JNA)." (PMID 29416703, 2018). "Among 27 samples from patients with Juvenile Nasopharyngeal Angiofibroma (JNA), 8 of 22 samples (36.4%) exhibited H19 over-expression and 7 of 19 samples (36.8%) exhibited IGF2 over-expression." (PMID 27802187, 2017).
kidney failure (2 papers, 2024). An acute or chronic condition that is characterized by the inability of the kidneys to adequately filter the blood. "A low IGF binding protein 3 (IGFBP3), such as in renal failure, may on the other hand cause a falsely normal or low IGF-2/IGF-1 ratio." (PMID 38432069, 2024). "A low IGF binding protein 3 (IGFBP3), such as in renal failure, may also result in a falsely normal or low IGF-2/IGF-1 ratio." (PMID 38432069, 2024).
laryngeal squamous cell carcinoma (2 papers, 2009 to 2012). A squamous cell carcinoma that arises from the larynx. "It is noteworthy that the P1 transcript is reported to be expressed from both parental alleles in postnatal liver and fetal choroid plexus/leptomeninges, and that P1 promoter activity was observed not to be exclusively connected to IGF2 LOI in laryngeal squamous cell carcinoma." (PMID 19936258, 2009).
lung squamous cell carcinoma (2 papers, 2014 to 2024). "In this study, IGF2 LOI was detected in half the cases of adenocarcinoma, but not in any cases of lung squamous cell carcinoma, which suggests an association between IGF2 LOI and the histological type of the tumor." (PMID 25364428, 2014).
manic episode (2 papers, 2024). "In patients with manic episode subgroup, we found a negative association between serum IGF-2 levels and YMRS scores (r = -0.522, P < 0.001)." (PMID 38563028, 2024). "Furthermore, IGF-2 was found to be an independent contributor to the severity of symptoms in patients with manic episodes (B = -0.610, t = -5.299, P < 0.001)." (PMID 38563028, 2024). "The present study demonstrates that patients with BD had lower serum IGF-2 levels in comparison to healthy controls, and serum IGF-2 levels were negatively correlated with the severity of manic symptoms in patients with manic episodes." (PMID 38563028, 2024). "Partial correlation analysis revealed that the correlation between IGF-2 levels and YMRS scores still existed in patients with manic episode when controlling for clinical variables including gender, age, age of onset, illness duration, and BMI (r = -0.612, P < 0.001)." (PMID 38563028, 2024).
microcephaly (2 papers, 2016 to 2025). A congenital or acquired developmental disorder in which the circumference of the head is smaller than normal for the person's age and sex. "This has previously been reported for HMGA2 and PLAG1, only one IGF2 case had relative microcephaly." (PMID 41430624, 2025). "One individual with IGF2 (9%) presented with relative microcephaly." (PMID 41430624, 2025).
motor neuron disease (2 papers, 2016 to 2019). "This includes proteins such as IGF2 which has been shown to be an important modifier in motor neuron disease." (PMID 31176719, 2019). "To test if IGF-2 could also protect against degeneration across motor neuron diseases, we used motor neurons derived from SMA patient iPSCs, which degenerate due to a lack of SMN1 protein." (PMID 27180807, 2016).
mucopolysaccharidosis type 2 (2 papers, 2023 to 2025). A lysosomal storage disease leading to a massive accumulation of glycosaminoglycans and a wide variety of symptoms including distinctive coarse facial features, short stature, cardio-respiratory involvement and skeletal abnormalities. "For this reason, the SWAP design, and SWAP-RAP12x2 in particular, represents a favourable transgene candidate for lentiviral gene therapy for Hunter syndrome, as well as for approaches involving IGF2-based therapeutics where peak plasma levels strongly exceed those achieved by HSPC‐LVGT (e.g., ERT)." (PMID 41023195, 2025).
Myocardial fibrosis (2 papers, 2022 to 2025). "IGF-2/IGF-2R can also increase plasminogen activator (PA) expression to promote the occurrence of myocardial fibrosis through disrupting the balance of MMP-9/TIMP-2 expression." (PMID 36358907, 2022). "IGF2 may also be involved in the progression of myocardial fibrosis by disrupting the TIMP2/MMP9 balance." (PMID 39744430, 2025). "IGF-2 analog [Leu27]IGF-2 can specifically activate IGF-2R, and the transfection of [Leu27]IGF-2 into rat cardiomyocytes by adenovirus can induce reconstruction characterized by pathological hypertrophy, myocardial fibrosis, and cardiomyocytes’ apoptosis accompanied by massive collagen deposition." (PMID 36358907, 2022).